CD38 (CD38 molecule)
Diseases named in the same sentence as CD38 in open-access papers (continued):
Sharing a sentence is not in itself a finding about the gene and the disease.
cancer (continued). "Because the observed increase in NB cytotoxicity was mediated by inhibition of CD38 and the resulting increase in NK cell proliferation, this approach may be useful in other cancers that express CD38." (PMID 36845935, 2023). "We postulate that this approach may also be of value in other cancers featuring CD38 expression and disproportionate NK cell populations." (PMID 36845935, 2023). "Based on this, advances in the area of CD38/NGAL-R Bi-Abs might be of significant consideration for future targeted therapies in these types of cancer, which abnormally express CD38 and NGAL-R." (PMID 37760777, 2023). "Indeed, the expression of CD38 in CD8+ T cells in TME has been associated with an immunosuppressive and dysfunctional phenotype that drives cancer progression." (PMID 37377962, 2023). "Furthermore, the addition of ATRA sensitizes the response of CD38low cancer cells to either CD38-CAR T cells or anti-CD38 antibodies." (PMID 35765110, 2022). "Moreover, we demonstrate that GoF C2 acts in concert with other therapeutic mAbs, such as type II anti-CD20, anti-CD22, and anti-CD38 specimens, for overcoming cancer cells resistance to complement attack." (PMID 35267578, 2022). "CD38-targeting monoclonal antibodies against cancer exemplify one such success story in the clinic." (PMID 36139103, 2022). "There are a couple of suggestions to improve the efficiency of anti-covid vaccination in cancer patients, particularly patients with hematologic malignancies, and subsequent to receiving immunosuppressive anti-cancer therapies such as anti-CD20 or anti-CD38 therapies." (PMID 35586627, 2022). "Finally, we investigated the potential anti-cancer benefit of ATRA in combination with CD38-CAR T cells or daratumumab." (PMID 35765110, 2022). "This has generated an impetus for the evaluation of CD38-targeting therapeutics in such cancers." (PMID 36139103, 2022). "As major NAD+ consumers, SIRTs, PARPs, and CD38 function in many critical processes in cancers." (PMID 36556252, 2022). "In addition, some investigators found that CD38 was more active in the erythrocytes of patients with cancer and systemic diseases, and the increased CD38 expression was notably significant." (PMID 34375303, 2021). "Importantly, DJ34 significantly reduced the relative number of CD34+ CD38− LSCs in the total pool of bone marrow–derived cancer cells, showing that LSCs are particularly sensitive to DJ34." (PMID 33303632, 2021). "Therefore, this study offers an effective method for the theranostic of CD38‐positive cancer, particularly MM." (PMID 34026426, 2021). "Furthermore, LCK, Perforin, and CD38 were identified as potential prognostic IHC biomarkers and should be evaluated in larger patient cohorts of both precancer and cancer patients." (PMID 34830895, 2021). "We also found targeting enzymatic activity of CD38 and its enzymatic product cADPR might be a promising strategy for the cancer therapy." (PMID 34226519, 2021). "Authors hypothesized that CD38 expression by cancer cells mediates immune-suppression via ADO production and its effect on CD8+ cytotoxic T cells." (PMID 33418913, 2021). "In addition, PD-1+CD38+ lymphocytes suppress anti-cancer activity and have been identified in patients with malignancies, especially after administration of anti-PD-1 MoAbs." (PMID 34638353, 2021). "CD38 is localized in cell membrane, nucleus, and mitochondria, and plays a key role in several physiological processes, including immune responses, inflammation, cancer, and metabolic disease." (PMID 32507768, 2020). "In this study, we demonstrated that decreased levels of NK cells, CD8+ T cells, naïve CD4+/CD4+ T cells, and elevated percentages of the following T cells were associated with cancer incidence: memory CD4+/CD4+, CD8+ HLA‐DR+/CD8+, CD8+ CD38+/CD8+, and CD4+/CD8+." (PMID 32459060, 2020).
cancer (continued). "Finally, supportive evidence on the critical role of CD38+ cells has been shown in anti-CD38 daratumumab treatments, where anti-cancer activity has been primarily related to the depletion of CD38+ MDSCs." (PMID 31783629, 2019). "CD38 also mediates resistance to certain forms of cancer immunotherapy." (PMID 31861847, 2019). "Greater knowledge of the roles and presence of biomarkers like CD38 in relation to cancer progress could capitalize on the efficiency offered by multiplexing techniques, and ultimately enhance cancer prognosis and provide timely treatment." (PMID 31861847, 2019). "SG003 seemed to be a good option to improve the curative effect of CD38-related cancers." (PMID 31118070, 2019). "In cancer experiments, we produced lytic immunoglobulin G (IgG) (which is cancer-cell killing) abs (detected with a complement fixation test) against cancer specific ags in donor rabbits injected with CD38 (cluster of differentiation 38) ag in Freund’s complete adjuvant." (PMID 30577575, 2018). "The enumeration of circulating c-FLIP-expressing monocytes, in association with specific surface markers induced by FLIP, such as PD-L1, PD-L2 and CD38 can thus constitute a useful tool to refine the immunological landscape of cancer patients for a more correct diagnosis and treatment." (PMID 30518925, 2018). "Overall, cancer tissues contained significantly lower CD38 staining scores than normal prostate." (PMID 30258629, 2018). "There have been a few relatively small studies of CD38 in the normal and malignant prostate." (PMID 29464091, 2018). "When cancer samples were split into two groups defined as above or below the median CD38 staining score, we found that higher CD38 (above the median) in cancer specimens was statistically significantly inversely associated with risk of recurrence (OR = 0.76, 95% CI 0.59–0.98, p = 0.031)." (PMID 30258629, 2018). "Isolated cells expressing low levels of CD38 display increased expression of inflammatory genes, generate significantly more organoids than high CD38 expressing cells, and can generate normal prostate glands and carcinomas in an in vivo reconstitution mouse model." (PMID 29464091, 2018). "An intriguing result from our study was that post-surgery cancer patients had significantly higher levels of recently activated effector CD4+ T cells as well as Tregs (CD38+) than controls, and they remained significantly increased until the completion of the study (18 weeks)." (PMID 24213326, 2012). "However, the immunosuppressive function of IL10+ IgD- CD38+ Bregs could be blocked, and cancer immunotherapy enhanced, by using PPARδ inhibitors." (PMID 38826800, 2024). "Additionally, although the diagnostic and therapeutic implications are less‐well understood, CD38 is expressed in other cancer types including prostate cancer, and molecularly targeted agents may have a more pan‐cancer role in the long term." (PMID 38421139, 2024). "Importantly, prolonged saturation of CD38 was witnessed in clinical setting several weeks after termination of daratumumab treatment, underscoring the necessity of tailoring the first dose to cancer binding capacity for efficient prolonged TRT." (PMID 38826403, 2024). "Thus, targeting CD38 along with PD1 could be a potential strategy to improve the efficacy of cancer immunotherapy." (PMID 38451948, 2024). "However, very little is known whether and how CD38 targeting affects B-cell differentiation, in particular for humans beyond cancer settings." (PMID 37419630, 2023). "Furthermore, non-polarized M0 macrophages showed increased expression of CD38 after co-culture with cancer cell spheroids, which can be linked to the myeloid-derived suppressor cell (MDSC)-like phenotypic changes." (PMID 37445941, 2023).
cancer (continued). "Other important parameters that need to be investigated include whether treatment outcome could be improved by targeting the mismatched killer cells with relevant monoclonal antibodies against cancer-associated cell surface antigens such as CD20, CD19, CD38 to mention just a few." (PMID 37202579, 2023). "The study of CD38 as a receptor started more than three decades ago and, as is true for several other cell membrane enzymes, more recently it has been refocused toward its expression and function in cancer cells, leading to the proposal of CD38 as a target for anti-cancer drugs." (PMID 34887854, 2021). "Our data revealed that ex vivo expansion of HSCs using the FBS culture system induces an inflammatory response and high CD38 expression, indicating that this system might activate an inflammatory pathway and induce expression of the cancer marker CD38 during ex vivo expansion of HSCs." (PMID 34375303, 2021). "In summary, significant differences in the levels of NK cells, CD8+ HLA‐DR+/CD8+ T‐cell percentages, and CD8+ CD38+/CD8+ T‐cell percentages were predictive in all untreated cancer patients and may represent biomarkers for noninvasive early screening in carcinogenesis." (PMID 32459060, 2020). "These nanotubes are dependent on CD38 for their formation and both genetic knock-down of CD38 and treatment with CD38 antibody interfere with the formation of these nanotubes and with mitochondrial transfer, and thereby, inhibit proliferation and reduce survival of the cancer cells." (PMID 32041300, 2020). "Besides their therapeutic activity in cancer, anti-CD38 mAbs may also provide interesting experimental tools to dissect CD38’s functions in other contexts." (PMID 33329591, 2020). "Hence, therapies against both MM cells and microenvironment control, such as daratumab, an antibody drug against CD38 that induces antibody-dependent cytotoxic events in CD38-expressing cancer cells and complement-dependent cytotoxicity, show success in MM treatment." (PMID 32781681, 2020). "Thus, the increased expression of NKp46 on CD56dim NK cells, together with CD38, could explain the enhanced response to cancer cells during pregnancy." (PMID 31708922, 2019). "Thus, it is conceivable that blocking the enzymatic activity of CD38 may be of therapeutic benefit in cancer." (PMID 29084989, 2017). "However, little is known about whether CD38+ TIMs promote cancer progression." (PMID 40327401, 2025). "By regulating the expression of FOXO1 and CD38, inactivating SRSF1 in T cells dramatically increases the cytotoxicity of CD8 + T cells in malignancies." (PMID 39837814, 2025). "Hematologic cancer cells (Daudi, L-1236, Raji, and NCI-H929 cell lines) were incubated with anti-CD38 antibodies in the presence of complement-containing human serum." (PMID 38983860, 2024). "CAR T-cells can also target other antigens in various cancers, such as CS-1, CD30, CD38, and CD138Prior studies have successfully identified a range of target antigens present on cancer cells." (PMID 38438559, 2024). "Other targets, including TNF receptor superfamily member 17 (TNFRSF17), CD22, CD38, CD33, and C-type lectin domain containing 14A (CLEC14A), demonstrated consistent but lower targeting potential across cancers." (PMID 39439803, 2024). "Based on the drug information, 29 sex-biased mRNAs were drug-targeted genes and six (CD38, PGR, ESR1, GABRP, F3, PRKCB) of them were targeted by cancer therapeutic drugs." (PMID 39175079, 2024). "We found that CD38+ T cells and CD133+ cancer stem cells (CSCs) were the most abundant cell populations in TS and TN, respectively." (PMID 36588094, 2023). "The close relationship between CD38 and PD-1/PD‐L1 not only occurs in HNSC, but also in other cancers." (PMID 36605482, 2023). "We found that CD38 expression in patients with HNSC was significantly higher than that in healthy subjects according to disease sorted by stage, race, sex, age, and cancer grade." (PMID 36605482, 2023).
cancer (continued). "Many currently used therapies, including bispecific T-cell engagers, anti-CD38 antibodies, proteasome inhibitors, and CART-cells, directly or indirectly depend on the anti-cancer activity of T-cells." (PMID 37954586, 2023). "A high percentage of CD38+/CD8+T can predict cancer progression and immunosuppressive status, implying that the immune system is activated during cancer development." (PMID 37346066, 2023). "Preclinical evaluation of CD38 CAR T in MM, AML, NKTL, and MCL suggests that this can effectively suppress CD38hi-expressing subsets of the cancer." (PMID 36139103, 2022). "Given that NAD+-mediated signaling events include transcription, cell cycle progression and metabolic regulation, silencing CD38, a key molecule that consumes NAD+, is seemingly the right strategy for fast-dividing cancer cells to increase NAD+ availability." (PMID 35677882, 2022). "Each cancer cell line was labeled with fluorescein‐conjugated antibodies against EGFR (α‐EGFR‐FL), HER2 (α‐HER2‐FL), CD38 (α‐CD38‐FL) and were cocultured with FL‐CAR T cells." (PMID 35146940, 2022). "Preclinical evaluation of this strategy has confirmed that ATRA can significantly enhance CD38 expression and trigger overall amplification of Fc-receptor-dependent effector mechanisms ADCC and CDC in a variety of cancer models." (PMID 36139103, 2022). "It has been well documented that binding of anti-CD38 mAb Daratumumab, anti-CD20 mAb rituximab, anti-HER2 mAb trastuzumab, anti-EGFR mAb cetuximab etc. to cancer cells promotes trogocytosis mediated by monocytes and other FcγR+ cells." (PMID 35273608, 2022). "22Rv1 cancer cell line demonstrates moderate antigen expression levels; the reference immunophenotype is CD29+low/CD54+low/CD146+low/CD166+low/CD38+low/CD10-/CD13-." (PMID 34019593, 2021). "AMG424 is a novel CD38/CD3 BiTE, and recently it has been reported that AMG 424 can kill cancer cells expressing high and low levels of CD38 in vitro and increases T-cell proliferation, but with attenuated cytokine release." (PMID 34307150, 2021). "However, we doubt whether this may be sufficient to counteract an increased activity of NAD+-degrading enzymes, for instance poly (ADP-ribose) polymerase 1 (PARP1) and CD38, due to inflammatory conditions induced by cancer cell metabolism itself as well as by treatment." (PMID 34835963, 2021). "PC-3 cancer cell line demonstrates high antigen expression levels; the reference immunophenotype is CD29+high/CD54+high/CD146+/CD166+low/CD38+high/CD10-/CD13-." (PMID 34019593, 2021). "CD38 and its homolog CD157 are being studied as possible cancer targets, and antibodies and inhibitors are being developed." (PMID 33384409, 2021). "The upregulation of CD38 decreases NAD+, resulting in conditions that promote cancer growth; therefore, we evaluated the effect of hSFRP2 mAb on NAD+." (PMID 34070758, 2021). "Both TNFRSF12A/TWEAK pair and CD38, along with its interaction partner CD31 are involved in multiple cancers, including NSCLC, where they contribute to escape from PD-1/PD-L1 blockade and cytotoxic therapy." (PMID 32537452, 2020). "Abnormal levels of NK cell, CD8+ T cells, memory CD4+/CD4+, naïve CD4+/ CD4+, CD8+ HLA‐DR/CD8+, CD8+ CD38+/CD8+, and CD4+/CD8+ can be a potential blood biomarkers of cancer development." (PMID 32459060, 2020). "Inversely, there were elevated levels of the following T‐cell percentages in cancer patients compared to those in healthy controls: memory CD4+/CD4+, CD8+ T cells, HLA‐DR/CD8+, CD8+ CD38+/CD8+, and CD4+/CD8+." (PMID 32459060, 2020). "Another future direction is to interpret the distinct function of the plasma-like specific, as well as the specifically expressed genes (such as CD38, MZB1), and their possible roles in cell-cell interactions and cancer-microenvironment co-evolution in NSCLC." (PMID 32580738, 2020).
cancer (continued). "Abnormal levels of NK cell, CD8+ T cells, memory CD4+/CD4+, naïve CD4+/CD4+, CD8+ HLA‐DR/CD8+, CD8+CD38+/CD8+, and CD4+/CD8+ can be a potential blood biomarkers of cancer disease progression." (PMID 32459060, 2020). "In contrast, a higher percentage of memory CD4+/ CD4+ T cells (P < .001), CD8+ HLA‐DR/ CD8+ T cells (P < .001), CD8+ CD38+/ CD8+ T cells (P < .001), and the CD4+/ CD8+ ratio (P < .001) were observed in cancer patients compared to healthy controls." (PMID 32459060, 2020). "The majority of therapeutic strategies for cancer treatment targets surface molecules expressed by solid tumors or leukemic cells, e.g. erbB2, and CD20, etc., one of which is human CD38." (PMID 31118070, 2019). "An improved understanding of CD38 and CD157 in the TME, and how these glycoproteins affect cancer progression, will be useful to develop both cancer prognosis and treatment methods." (PMID 31861847, 2019). "Among the enzymes involved in NAD homeostasis, NAMPT, CD38, sirtuins, and IDO are overexpressed in different types of cancer and have been shown to play a role in cancer immune tolerance." (PMID 31402913, 2019). "Information on the roles of CD38 and CD157 in different cancers is consolidated from relevant data and evidence available in existing literature." (PMID 31861847, 2019). "This review aims to discuss the roles of CD38 and CD157 in the TME and cancer immunotherapy of a range of solid tumor types." (PMID 31861847, 2019). "When PBMC from normal subjects or cancer bearing patients were differentiated into CIK cells under normoxic conditions, CD38 and CD39 were greatly up-regulated while the number of CD203a, and CD73 positive cells underwent minor changes." (PMID 29731713, 2018). "After demonstrating increases in potency and specificity with the initial EDC-DYS conjugate, several other EDCs were constructed with other antibodies specific to important cancer related proteins (CD20, CD38, CD147, CD56)." (PMID 27434591, 2016). "The LN2A model revealed several observations about the potential role of TIMs in LUSC progression, particularly regarding a CD38+ TIM subcluster, which may also have roles in various other cancers." (PMID 40327401, 2025). "However, the authors selected various cancer cell lines (including Raji, Daudi, NCI-H929, L-1236, Reh and MOLM-13) due to the expression profile of CD38 and CD47 making them the suitable candidates for study." (PMID 38983860, 2024). "In addition, we predicted the sensitivity of common anti-cancer drugs on prognostic signature, including CCR5, HMOX1, CTSC, CD5, BCL3, CDH1, TYROBP and CD38." (PMID 38767825, 2024). "This corrective action of cancer on SARS-CoV-2-related inflammation does not seem to be unidirectional as COV/CA patients display enhanced activation of HLA-DR+CD38+CD4+ T cells, and increased IFNγ expression in PBMCs." (PMID 37063865, 2023). "CD44 is highly expressed within normal, CML and AML CD34+CD38+ and CD34+CD38− BM cells [53•], likely making it unsuitable as a CML LSC biomarker and a cancer-specific therapeutic target, but downstream signalling may be targetable." (PMID 36780103, 2023). "In contrast, the expression levels of TXNDC5, CD38, GAS6, FKBP2 and SDC1 were increased in the late stage of LUAD progression, indicating potential distinct roles in the occurrence and progression of the cancer." (PMID 37728413, 2023). "Combination of CD38 CAR T with CD38 transcriptional activators, such as ATRA, further improve therapeutic efficacy in mouse xenografts, emphasizing the importance of optimal induction of CD38 expression in cancer cells." (PMID 36139103, 2022). "There are growing reports using nanobody-based immunotoxins to treat cancers by targeting a variety of antigens such as glypican-3, glypican-2, EGFR, HER2, VEGFR2, CD7 and CD38, which indicates the great potential of nanobody-based immunotoxins for cancer therapy." (PMID 36435809, 2022).